AXL (AXL receptor tyrosine kinase)
Diseases named in the same sentence as AXL in open-access papers (continued):
Sharing a sentence is not in itself a finding about the gene and the disease.
steatosis (2 papers, 2021 to 2025). Increased lipid within the cytoplasm of cells. "Furthermore, the ALD model was established by chronic-plus-binge ethanol feeding to explore the role of AXL in I/R liver injury with ethanol-associated steatosis." (PMID 39897049, 2025). "Amongst all three receptors, AXL exhibits higher affinity towards Gas6 and the Gas6/AXL pathway is known to be involved in the development of steatosis to fibrosis." (PMID 34944593, 2021). "The increased activation of AXL is observed during high fat diet-induced steatosis, suggesting its correlation with the development of NAFLD." (PMID 34944593, 2021). "They observed that blocking of the Gas6/AXL pathway significantly reduced triglyceride content, and overall steatosis score in mice fed on a high fat diet." (PMID 34944593, 2021). "EGFR is found to regulate NAFLD at various stages, starting from steatosis to NASH, and even with regard to fibrosis, while other RTKs discussed, such as AXL, FGFR4 and VEGFR, are also found to be effective in regulating different manifestations of NAFLD." (PMID 34944593, 2021).
tongue cancer (2 papers, 2016 to 2023). A malignant neoplasm affecting the tongue. "In conclusion, our results establish that the miR-944/MMP10/AXL- axis underlies lymph node metastases with potential therapeutic intervention and prediction of nodal metastases in tongue cancer patients." (PMID 36650344, 2023). "We also show that miR-944 negatively regulates MMP10, and AXL signaling pathway mediates phenotypes associated with MMP10 overexpressing tongue cancer." (PMID 36650344, 2023). "MMP10, which is upregulated in 86% of primary tongue tumors with lymph node metastases, is negatively regulated by miR-944 and promotes nodal metastasis in an orthotopic tongue cancer mouse model through the AXL signaling pathway." (PMID 36650344, 2023). "Taken together, these findings indicate that MMP10-mediated migration and invasion of tongue cancer cells is regulated by activation of the AXL signaling pathway and upregulation of EMT marker genes." (PMID 36650344, 2023). "Here, we present the molecular mechanism of miR-944/MMP10/AXL- axis mediated tongue cancer metastasis." (PMID 36650344, 2023). "We screened for the expression of AXL transcript and protein in tongue cancer cell lines." (PMID 36650344, 2023). "In the current study, we validate MMP10 expression in a large cohort of tongue patient samples with nodal metastases and describe the mechanistic role of miR944/MMP10/AXL- axis in tongue cancer using in vitro biochemical and cell-based assays and in vivo orthotopic tongue tumor mouse model." (PMID 36650344, 2023). "Interestingly, SCC-25 cells (derived from a primary tongue cancer) express low endogenous AXL protein levels and HN cells (derived from a lymph node metastasis) have high AXL protein expression, which reflects the pattern seen in patients." (PMID 28025482, 2016). "Targeting AXL may represent a novel therapeutic approach in managing tongue cancer patients." (PMID 36650344, 2023). "Thus, our findings indicate that AXL could be a potential therapeutic target in tongue cancer patients." (PMID 36650344, 2023). "And, overexpression of AXL promotes MMP10-suppressed proliferation, invasion, and migration of tongue cancer cells." (PMID 36650344, 2023). "We set to study the role of AXL in MMP10-promoted invasion and migration of tongue cancer." (PMID 36650344, 2023). "Interestingly, knockdown of AXL suppresses MMP10-promoted proliferation, invasion, and migration of tongue cancer cells." (PMID 36650344, 2023). "Furthermore, ectopic expression of miR-944 or knockdown of AXL suppresses MMP10-promoted proliferation, invasion, and migration of tongue cancer cells, indicating a therapeutic approach to target tongue cancer." (PMID 36650344, 2023).
uterine cancer (2 papers, 2016 to 2019). Primary or metastatic malignant neoplasm involving the uterine corpus and/or the cervix. "One candidate target protein involved in ovarian and uterine cancer metastasis is the TAM receptor tyrosine kinase family member AXL." (PMID 30886159, 2019). "Recently, we found that high AXL expression in tumors correlates with poor survival in patients with high-grade uterine cancer." (PMID 30886159, 2019). "Recently, AXL was shown to have a role in ovarian and uterine cancer metastasis, making it a therapeutic target to combat metastasis in these cancers." (PMID 30886159, 2019). "One therapeutic target is the protein AXL, which has been shown to be involved in metastasis in both ovarian and uterine cancer." (PMID 30886159, 2019). "Here, we present evidence that p5RHH-siAXL nanoparticles inhibit AXL expression both in vitro and in vivo in ovarian and uterine cancer models." (PMID 30886159, 2019). "AXL overexpression has been reported in human uterine cancer, but the role of AXL in EC progression has yet to be elucidated." (PMID 27764792, 2016). "Additionally, AXL inhibition in uterine cancer cells decreased in vitro migration and invasion and in vivo metastatic potential in a mouse xenograft model." (PMID 30886159, 2019). "To determine whether AXL activation in uterine cancer is ligand dependent, we starved ARK1 and Hec50a cells for 48 hours." (PMID 27764792, 2016). "Thus, targeting AXL could combat metastasis in both ovarian and uterine cancer." (PMID 30886159, 2019).
acute coronary syndrome (1 paper, 2025). Signs and symptoms related to acute ischemia of the myocardium secondary to coronary artery disease. "To investigate the dynamics of the two distinct forms of sAXL in CVD, we analyzed the levels of sAXL and the Gas6/AXL complex in patients with acute coronary syndrome (ACS)." (PMID 40933570, 2025).
acute myocardial infarction (1 paper, 2025). Necrosis of the myocardium, as a result of interruption of the blood supply to the area. "The threshold value for the Gas6/AXL complex was determined to be 1.8 ng/mL; concentrations exceeding this threshold were associated with an increased risk of myocardial infarction." (PMID 40933570, 2025). "Consequently, the implications of variations in the levels of the Gas6/AXL complex in CVD, such as acute myocardial infarction (AMI), remain largely unexplored." (PMID 40933570, 2025).
adenoid cystic carcinoma (1 paper, 2024). A malignant tumor arising from the epithelial cells. "First use of AXL-targeting in adenoid cystic carcinoma (ACC); with positive results, ACC now included in AXL studies." (PMID 38579194, 2024).
African trypanosomiasis (1 paper, 2014). "Regarding the 16 up-regulated genes, S100A3, AXL, IL12A, XPC and FAS identified GO terms such as positive regulation of natural killer cell activation, response to UV-B, African trypanosomiasis, allograft rejection and Type I diabetes mellitus." (PMID 24756038, 2014).
aneurysm (1 paper, 2023). Bulging or ballooning in an area of an artery secondary to arterial wall weakening. "We also found that smooth muscle cells in mouse aneurysms expressed AXL in contrast to those in normal vessels." (PMID 37223093, 2023).
angiosarcoma (1 paper, 2025). A malignant tumor arising from the endothelial cells of the blood vessels. "Moreover, highly aggressive angiosarcomas exhibit considerable genomic plasticity, allowing them to activate alternative signaling pathways (e.g., MET, AXL, and MAS), thereby bypassing VEGFR inhibition by sunitinib." (PMID 41341391, 2025).
B-cell acute lymphoblastic leukemia (1 paper, 2023). A neoplasm of lymphoblasts committed to the B-cell lineage, typically composed of small to medium-sized blast cells. "Previously, we have demonstrated that dexamethasone-resistant B-cell acute lymphoblastic leukemia cells that express the oncogenic mutant of FLT3 display upregulation of AXL expression upon inhibition of FLT3." (PMID 36835239, 2023).
bile duct cancer (1 paper, 2023). "The reduced activation of these pathways in bile duct cancer cells stably expressing shRNA against AXL suggests that activated AXL is a critical regulator of these pathways." (PMID 36980768, 2023). "The analysis of AXL-expressing bile duct cancer cells (SNU1196, HUCCT1) revealed that AXL plays significant roles in tumor growth, invasion and metastasis." (PMID 36980768, 2023). "Therefore, these in vitro studies demonstrate that AXL is required for cell growth, invasion and migration in bile duct cancer cells." (PMID 36980768, 2023). "Our studies indicate that AXL might be a good therapeutic target for controlling intrahepatic bile duct cancer at its primary site." (PMID 36980768, 2023). "In searching for new molecular targets for bile duct cancer diagnosis and therapy, we found that the receptor tyrosine kinase AXL is highly expressed in bile duct cancer cells and that inhibition of its expression and signaling significantly reduces tumor growth and the spread of cancer cells." (PMID 36980768, 2023). "This study suggests that AXL is a potential new therapeutic target for treating bile duct cancers." (PMID 36980768, 2023). "To determine whether AXL plays an essential role in the progression of bile duct cancer, we tested this hypothesis using the same AXL knockdown cells." (PMID 36980768, 2023). "This study examined whether AXL plays a significant role in the progression of bile duct cancers using both in vitro and in vivo systems." (PMID 36980768, 2023). "Therefore, AXL is a potential therapeutic target for the treatment of bile duct cancer." (PMID 36980768, 2023). "In vitro studies with bile duct cancer cells (SNU1196 and HUCCT1) showed that genetic knockdown of AXL significantly reduced both tumor cell growth and invasion." (PMID 36980768, 2023). "Additionally, we investigated the efficacy of AXL inhibition using both genetic knockdown and AVB-500, a soluble AXL decoy receptor, confirming AXL as a potential therapeutic target for bile duct cancer." (PMID 36980768, 2023).
bile duct tumor (1 paper, 2023). "Overall, the present study demonstrates AXL inhibition as a potential therapy to inhibit both bile duct tumor growth and metastasis." (PMID 36980768, 2023).
bone metastasis (1 paper, 2025). Transfer of a neoplasm from its primary site to bones. "It is difficult to determine whether the difference in AXL expression ultimately influenced the late treatment outcome; however, the development of bone metastasis in case 2 suggests that the loss of AXL expression may have limited the efficacy of cabozantinib." (PMID 40921965, 2025).
bone tumor (1 paper, 2023). "Notably, the AXL signaling pathway appears important in bone tumor pathogenesis due to its regulation of bone cancer cell colony formation and EMT." (PMID 36831169, 2023).
cardiac arrest (1 paper, 2025). Cessation of breathing and/or cardiac function. "When extracting proteins unlikely to show post-cardiac arrest changes based on their levels in relation to lactate and sampling time, two proteins (AXL and TIMP-4) were identified." (PMID 39992996, 2025).
cardiac hypertrophy (1 paper, 2019). "In view of the association between AXL and cardiac hypertrophy, we aimed at further exploring Axl co-expression patterns with hypertrophic factors." (PMID 31181097, 2019).
chronic heart failure (1 paper, 2023). "In particular, several reports in the literature have suggested that modulating specifically the GAS6/AXL interaction would improve chronic heart failure." (PMID 36983628, 2023).
chronic hepatitis C (1 paper, 2023). "Clinical trials have demonstrated elevated GAS6 and AXL levels in patients with chronic hepatitis C (HCV) and acute liver disease (ALD)." (PMID 37108648, 2023).
cognitive deficits (1 paper, 2026). "Microglial AXL cKO mice exhibited worse motor and cognitive deficits up to 28 days after tMCAO, accompanied by more severe white matter damage, increased myelin debris, and greater lipid droplets (LDs) accumulation in microglia than WT controls." (PMID 41524160, 2026).
coronary artery disease (1 paper, 2022). "Finally, we established a causal patho-mechanistic network of GE and PE of IL6R, PCSK9, TFPI, and AXL and coronary artery disease providing possible new therapy targets." (PMID 35604899, 2022).
cyst (1 paper, 2024). A sac-like closed membranous structure that may be empty or contain fluid or amorphous material. "Some factors (e.g., ICAM1, CCL20, PSME2, AXL) can also enhance proliferative signaling pathways (via MAPK/ERK, JNK, and JAK/STAT signaling, among others) that lead to cyst growth stimulation." (PMID 38385746, 2024).
depression (1 paper, 2015). "The list includes several genes previously implicated in depression including the NTRK2, AXL and TAC1 genes." (PMID 25734512, 2015).
dermal neurofibroma (1 paper, 2014). A dermal neurofibroma is a neurofibroma that occurs in situ of the skin. "Strong AXL expression was also observed in one MPNST and three out of four dermal neurofibroma samples that were derived from 5 different NF1 patients." (PMID 25551830, 2014).
E. coli infection (1 paper, 2021). "Of note, several microbial infection-related pathways, including bacterial invasion of epithelial cells, viral carcinogenesis, viral myocarditis, pathogenic E. coli infection, salmonella infection and vibrio cholerae infection pathways, were also enriched after AXL was activated." (PMID 34439388, 2021).
Ebola (1 paper, 2025). "Beyond cancer, AXL’s role in viral entry and replication (e.g., Ebola and SARS-CoV-2) and its impact on immune response modulation in comorbid conditions requires further investigation." (PMID 39924521, 2025).
emphysema (1 paper, 2014). "Similarly, with regard to the LP15A emphysema outcome variable, meta-analysis with the TESRA cohort validated the association of RAGE (p = 2.5 × 10−10), ICAM1 (p = 6.0 × 10−11), and AXL (p = 3.8 × 10−3) with radiologic emphysema independent of covariates." (PMID 25306249, 2014).
endometrioid adenocarcinoma (1 paper, 2016). An adenocarcinoma characterized by the presence of malignant glandular epithelial cells resembling endometrial cells. "In contrast, AXL was expressed at very low levels in AN3CA (derived from a grade 3 endometrioid adenocarcinoma), KLE (derived from a poorly differentiated adenocarcinoma), and Ishikawa (derived from a well differentiated type I adenocarcinoma) cells." (PMID 27764792, 2016).
experimental autoimmune encephalomyelitis (1 paper, 2021). An autoimmune demyelinating disease of the central nervous system that is produced experimentally in animals by the injection of homogenized brain or spinal cord in Freund's adjuvant. "Anti-AXL antibody therapy reduces the severity of experimental autoimmune encephalomyelitis in mice." (PMID 34734092, 2021).
gallbladder tumor (1 paper, 2023). "These targets were identified based on the KEGG pathway database and our previous research, which demonstrated that YAP1 promotes gallbladder tumor growth by activating the AXL/MAPK pathway." (PMID 37147639, 2023).
germ cell tumor (1 paper, 2012). A benign or malignant, gonadal or extragonadal neoplasm that originates from germ cells. "FN1, AXL, and SOX9 demonstrated a similar pattern of expression across all lines and have been shown by others to be over expressed in germ cell tumors." (PMID 22737227, 2012).
glomerular disease (1 paper, 2023). "Among the 3 TAM receptors (TYRO3, AXL, and MER), only TYRO3 expression is largely restricted to podocytes, and glomerular TYRO3 mRNA expression negatively correlates with human glomerular disease progression." (PMID 36454644, 2023).
hyperlipidemia (1 paper, 2025). "Multivariate logistic regression analysis indicated that STEMI was associated with the Gas6/AXL complex, hyperlipidemia, and LVEF." (PMID 40933570, 2025). "Additionally, the Gas6/AXL complex, along with hyperlipidemia, serves as a risk factor for STEMI." (PMID 40933570, 2025). "Specifically, hyperlipidemia and Gas6/AXL complex levels were positively correlated, and identified as risk factors, with odds ratios (OR) of 157.045 (7.171–3439.520, p < 0.001) and 3.307 (1.209–9.051, p = 0.020), respectively." (PMID 40933570, 2025).
inflammatory breast carcinoma (1 paper, 2021). An advanced, invasive breast adenocarcinoma characterized by the presence of distinct changes in the overlying skin. "In inflammatory breast cancer cell lines, depletion of AXL-stabilizing protein TIG1 reduces the expression of Matrix metalloproteinase 9 (MMP9), which has been identified as an essential regulator for the AXL-mediated invasion." (PMID 33954117, 2021).
intestinal tumor (1 paper, 2022). "The mutation designated as a germline mutation but not detected in the tumor fraction was only for one alteration in AXL c.1503dupC (VAF, 2.42%) in the intestinal tumor (sample S1)." (PMID 35194076, 2022).
intrahepatic cholangiocarcinoma (1 paper, 2023). A carcinoma that arises from the intrahepatic bile duct epithelium in any site of the intrahepatic biliary tree. "A tissue microarray (TMA) of 75 patient tissue cores showed that phosphorylated AXL, a marker for AXL activation, is elevated in both bile ducts and intrahepatic cholangiocarcinoma tissues compared to 45 normal liver tissues." (PMID 36980768, 2023).
ischemic stroke (1 paper, 2026). A stroke disorder caused by obstruction of blood flow to the brain, due to thrombotic (local blood clot formation) or embolic (due to a blood clot or other material traveling from another site) event. "Collectively, these findings identify microglial AXL as an endogenous regulator of myelin repair after ischemic stroke." (PMID 41524160, 2026).
Kaposi's sarcoma (1 paper, 2023). A malignant neoplasm characterized by a vascular proliferation which usually contains blunt endothelial cells. "It was also demonstrated that AXL is over-expressed in Kaposi sarcoma and Kaposi sarcoma herpesvirus-transformed endothelial cells." (PMID 36980534, 2023). "MAbs generated to induce AXL degradation inhibited Kaposi-sarcoma-cell invasion in in vitro models and tumor growth in vivo." (PMID 36980534, 2023).
kidney tumor (1 paper, 2025). "The results indicated that AXL expression is among the highest in kidney tumor tissues and significantly higher compared to normal tissues or adjacent normal tissues." (PMID 41029360, 2025).
lentivirus infection (1 paper, 2024). Virus diseases caused by the Lentivirus genus. "Subsequently, we employed a range of experimental techniques including lentivirus infection, recombinant protein stimulation, and AXL inhibition experiments to validate these interactions and unravel the underlying mechanisms." (PMID 38254761, 2024).
liver steatosis (1 paper, 2024). "Our study focused primarily on the effects of AXL inhibition on liver steatosis, inflammation, and fibrosis." (PMID 38817615, 2024). "In mice fed different fat-enriched diets, liver steatosis alone was insufficient to elevate plasma soluble AXL (sAXL) levels." (PMID 38817615, 2024). "In this setting, AXL inhibition reduced liver steatosis and fibrosis, as observed with H&E and Sirius Red staining." (PMID 38817615, 2024). "The findings support the potential of sAXL as an early biomarker for MASLD/MASH and highlight the therapeutic efficacy of AXL inhibition in attenuating liver steatosis, inflammation, and fibrosis." (PMID 38817615, 2024).
lung squamous cell cancer (1 paper, 2024). "Our findings indicated a role of CD73 in mediating NSCLC metastasis, especially for lung squamous cell cancer patients with high CD73 expression, combined targeting of AXL may provide the greatest benefit to patients." (PMID 39423241, 2024).
lymphoma (1 paper, 2019). A malignant (clonal) proliferation of B- lymphocytes or T- lymphocytes which involves the lymph nodes, bone marrow and/or extranodal sites. "AXL-overexpressing T lymphoma cells increased the susceptibility to cytotoxic T cells (CTL)- and NK cell-mediated cell lysis." (PMID 31694201, 2019).